NLRP3 (NLR family pyrin domain containing 3)
Diseases named in the same sentence as NLRP3 in open-access papers (continued):
Sharing a sentence is not in itself a finding about the gene and the disease.
osteoarthritis (100 papers, 2011 to 2026). A noninflammatory degenerative joint disease occurring chiefly in older persons, characterized by degeneration of the articular cartilage, hypertrophy of bone at the margins and changes in the synovial membrane. "For instance, the previous research indicated that autophagy was suppressed in osteoarthritis, and lowered level of autophagy was associated with NLRP3 inflammasome activation and inhibition of the Nrf2 signaling pathway." (PMID 33505502, 2021). "NLRP3 inflammasome has been implicated in osteoarthritis pathological progression through secreting proinflammatory cytokines including IL-1β and tumor necrosis factor-alpha (TNF-a), producing cartilage degrading enzymes like MMP3 and aggravating synovial membrane inflammation." (PMID 35935815, 2022). "Furthermore, ROS‐induced oxidative stress was believed to be the main cause of NLRP3 inflammasome activation during OA development, and activating the Nrf2/HO‐1 signalling alleviates osteoarthritis development by inhibiting NLRP3 inflammasome activation." (PMID 35775127, 2022). "The authors, in this paper evaluating the effects of spermidine in an in vivo model of osteoarthritis demonstrated that treatment was able to inhibit inflammation and pyroptosis by modulating the NF-κB and NLRP-3 cascades." (PMID 40871615, 2025). "FOXQ1 reportedly inhibits Osteoarthritis (OA) progression by downregulating pyroptosis induced by NLR family pyrin domain containing 3 (NLRP3)." (PMID 41347087, 2025). "This highlights the importance of the NLRP3 inflammasome and NF-κB pathways in linking osteoarthritis to intervertebral disc pathology." (PMID 41181141, 2025). "has unveiled that inhibiting the Nrf2/HO‐1 pathway results in increased activation of the NLRP3 inflammasome, along with upregulation of IL‐1β and IL‐18 expression in osteoarthritis." (PMID 41378869, 2025). "Extracellular vesicles derived from human umbilical MSCs interact with METTL3 to reduce NLRP3 m6A levels in macrophages, alleviating osteoarthritis in mouse models." (PMID 40502627, 2025). "The regulation of the NLRP3 inflammasome activation state is a promising target for neuronal necroptosis, osteoarthritis, and respiratory system diseases." (PMID 38708425, 2024). "TXNIP was also reported to activate NLRP3 inflammasomes in inflammation-related diseases, such as osteoarthritis." (PMID 38671856, 2024). "As of now, only a handful of studies have explored the potential role of the NLRP3 inflammasome in the pathogenesis of osteoarthritis (OA)." (PMID 38532994, 2024). "The KD was previously shown to inhibit NLRP3 inflammasome activation in a rat model of osteoarthritis." (PMID 38198459, 2024). "NLRP3-mediated pyroptosis plays a crucial role in the pathological process of osteoarthritis, and the activation of the NF-κB pathway exacerbates the inflammatory response." (PMID 38178210, 2024). "Chondrocytes and fibroblast like synoviocytes (FLSs) play a significant role in the molecular process of NLRP3-mediated pyroptosis in osteoarthritis." (PMID 37954594, 2023). "The significance of NLRP3-inflammasome in RA pathogenesis is demonstrated by the findings of increased mRNA NLRP3 in RA synovial tissue relative to osteoarthritis subjects." (PMID 37332933, 2023). "Daphnoretin can suppress IL-1β-induced chondrocyte apoptosis by inhibiting endoplasmic reticulum stress and NOD-, LRR- and pyrin domain-containing protein 3 (NLRP3) inflammasome activation and suppressing osteoarthritis." (PMID 37621874, 2023). "It has been shown that P2X7R whose expression is increased in brain tissues with AD and plays a role in the activation of NLRP3 inflammasome is suppressed by miR-373 in patients with osteoarthritis." (PMID 36422510, 2022). "The nucleotide-binding domain, leucine-rich repeat, and pyrin domain-containing protein 3 (NLRP3) inflammasome has been reported to be involved in the pathological process of osteoarthritis (OA) inflammation." (PMID 35585627, 2022).
osteoarthritis (continued). "The NLRP3 inflammasome has a significant role in the development of secondary osteoarthritis, and several studies have provided evidence of its role in the development of primary osteoarthritis, while other inflammasomes cannot be excluded." (PMID 35629398, 2022). "Receptor-interacting serine/threonine protein kinase 2 (RIPK2) regulates NLRP3 and inflammation, and the NOD/RIPK2 inflammatory signaling pathway has been found to confer susceptibility to osteoarthritis." (PMID 36619896, 2022). "Many studies have demonstrated the role of the NLRP3 inflammasome in osteoarthritis, indicating that NLRP3 is a potential target." (PMID 36158216, 2022). "Oxidative stress-mediated activation of the Nod-like receptor protein 3 (NLRP3) inflammasome was also associated with increased expression of NRF2, HMOX1, and IL1B in humans with osteoarthritis." (PMID 34744798, 2021). "We shall explore the regulation mechanism of the miR-140-5p/CTSB/NLRP3 axis in osteoarthritis clinically in our future endeavors." (PMID 34565303, 2021). "Studies have shown that Dex inhibits the NF-κB pathway and NLRP3 inflammasome to attenuate papain-induced osteoarthritis in rats." (PMID 33823789, 2021). "Assessment of the effect of dexmedetomidine on NLRP3 expression, Casp1 activation and levels of IL-1ß and mechanical allodynia in model of osteoarthritis induced by papain." (PMID 32973552, 2020). "In osteoarthritis, hydroxyapatite crystals are able to activate IL-1β and elevate its production through the NLRP3 inflammasome, thus mediating inflammation and joint diseases." (PMID 32148650, 2020). "The present study demonstrated that ICA inhibited LPS-mediated chondrocytes injury and pyroptosis and alleviated rat osteoarthritis by inhibiting NLRP3 and caspase-1 signaling." (PMID 31511005, 2019). "The importance of the NLRP3-inflammasome in RA pathogenesis is illustrated by the findings of increased NLRP3 mRNA in synovial tissue from RA patients compared to subjects with osteoarthritis." (PMID 24967817, 2014). "Moreover, the NLRP3 inflammasome represents a promising therapeutic target in the pathogenesis of osteoarthritis (OA)." (PMID 39857301, 2025). "Moreover, suppression of the Nrf2/HO‐1 pathway results in elevated NLRP3 inflammasome activation in osteoarthritis." (PMID 41378869, 2025). "Hence, the current study aimed to investigate the role of miRNA-373/P2X7/NLRP3/NF-κB trajectory in its pathogenesis as well as the possible anti-inflammatory effects of probenecid and l-carnitine in ameliorating osteoarthritis via modulating this pathway." (PMID 37994991, 2024). "Curcumin might target NLRP3 inflammasome by reducing NLRP3-mediated inflammation and oxidative stress and possibly ameliorating osteoarthritis pathophysiology." (PMID 38235147, 2023). "Hence, the NLRP3/Caspase-1 signaling pathway plays a crucial role in the initiation and advancement of osteoarthritis, making the pyroptosis process highly significant in this context." (PMID 37954594, 2023). "Several studies have shown that targeted inhibition of the TXNIP/NLRP3 signaling pathway may also improve the pathological manifestations of osteoarthritis and promote the repair of cartilage damage in OA cell models and mouse models." (PMID 37702097, 2023). "Furthermore, Mir-155 functions as a critical regulatory factor of NLRP3 and has been found to regulate NLRP3-mediated cell pyroptosis in various diseases, including osteoarthritis." (PMID 37960237, 2023). "In addition, lncRNA SNHG7 attenuated miR-214-5p-mediated PPARGC1B pathway and led to inhibition of IL-1β-induced osteoarthritis via suppression of NLRP3 inflammasome and apoptosis." (PMID 37779916, 2023). "PPARγ activation alleviated osteoarthritis through the Nrf2/NLRP3 pathway." (PMID 37905351, 2023). "In addition, research has shown that suppressing Nrf2/HO-1 signaling in osteoarthritis enhances NLRP3 inflammasome signaling." (PMID 35109747, 2022).
osteoarthritis (continued). "Ursolic acid at 5 μM concentration could alleviate osteoarthritis by inhibition of the NLRP3 inflammasome in chondrocytes." (PMID 35047046, 2022). "Our study provided the evidence that EA could alleviate osteoarthritis and chronic OA pain by suppressing NLRP3 inflammasome activation in guinea pigs with spontaneous osteoarthritis." (PMID 32952587, 2020). "Our findings demonstrate that EA may alleviate osteoarthritis by suppressing NLRP3 inflammasome activation in guinea pigs with spontaneous osteoarthritis." (PMID 32952587, 2020). "Moreover, NLRP3 level is positively related to ferroptosis in a rat model of osteoarthritis." (PMID 40622464, 2025). "In osteoarthritis, GBP5 expression is significantly upregulated in TNF‐α‐treated chondrocytes, where IRF1 promotes GBP5 transcription, triggering NLRP3 inflammasome activation and promoting pyroptosis." (PMID 40636987, 2025). "In inflammatory conditions, GBP5 promotes chondrocyte pyroptosis by upregulating pyroptosis-related genes, such as NLRP3, Caspase-1, and Gasdermin D (GSDMD), through the NLRP3 inflammasome pathway, contributing to osteoarthritis progression." (PMID 40788157, 2025). "Hence, both Nrf2 and NLRP-3 could be therapeutic targets for the treatment of osteoarthritis." (PMID 38235147, 2023). "For obesity-related osteoarthritis, diet rich in SFA, MUFA, and n-6 PUFA can activate the TLR4/NF-κB signaling pathway in articular cartilage, which in turn upregulates the NLRP3 inflammasome, thereby inducing pyroptosis." (PMID 37215994, 2023). "Suppression of lncRNA SNHG14 blocked FSTL-1-induced NLRP3 and TLR4/NF-kappaB pathways via regulation of miR-214–3p, conferring to inhibition of osteoarthritis." (PMID 37779916, 2023). "In the field of osteoarthritis, TXNIP/NLRP3 signaling pathway is closely related to chondrocytes and synoviocytes, but further investigation is needed." (PMID 34539417, 2021). "Although we found that Nrf2, HO-1, NLRP3, and ASC were expressed in the knee synovia of patients with osteoarthritis, concrete evidence for the relationship between these genes and OA is still missing." (PMID 31870428, 2019). "In osteoarthritis, moderate-intensity exercise reduces inflammation and pyroptosis by increasing the expression of Metrnl, an adipomyokine that inhibits the PI3K/Akt/NF-κB signaling pathway and subsequently the NLRP3/caspase-1/GSDMD pathway." (PMID 41399377, 2026). "In conclusion, l-carnitine augmented the probenecid’s anti-inflammatory effect to attenuate MIA-induced osteoarthritis in rats by provoking the miRNA-373 level and inhibiting the P2X7/NLRP3/NF-κB milieu, leading to the suppression of serum inflammatory cytokines: IL-1β, IL-18, IL-6, and TNF-α." (PMID 37994991, 2024). "Furthermore, high levels of pyroptosis-related cytokines (IL-1β, IL-18), produced by fibroblast-like synovial cells, have been found in the synovial fluid of patients with osteoarthritis, together with an increased expression of NLRP1 and NLRP3 inflammasomes." (PMID 39000412, 2024). "More recent keywords, such as ferroptosis (2021.01), pyroptosis (2020.97), and gut microbiota (2020.80), are highlighted on the map, while keywords like NLRP3 (2019.95), polysaccharides (2019.86), mitophagy (2019.84), NAFLD (2019.83), and osteoarthritis (2019.69) are relatively less recent." (PMID 37779908, 2023). "The relationship between NLRP-3 (NOD-, LRR- and pyrin domain-containing protein 3) inflammasome and Nrf2 (nuclear factor erythroid 2-related factor 2) signaling has been demonstrated in the osteoarthritis." (PMID 38235147, 2023). "However, in osteoarthritis, NEAT1 and NLRP3 seem to have a relieving effect." (PMID 38178210, 2024).
psoriasis (94 papers, 2015 to 2026). An autoimmune condition characterized by red, well-delineated plaques with silvery scales that are usually on the extensor surfaces and scalp. "(xii) The development and progression of psoriasis are associated with NLRP3 inflammasomes, which are large protein complexes that play a crucial role in regulating the innate immune response and inflammation." (PMID 40006568, 2025). "The NLRP3 (rs10754558) gene polymorphism serves as a significant diagnostic biomarker in individuals with psoriasis and has the potential to be a valuable tool in therapeutic therapy." (PMID 38965465, 2024). "This study is the first to investigate the association between the NLRP3 (rs10754558) gene polymorphism and response to psoriasis therapy." (PMID 38965465, 2024). "In psoriasis, a chronic inflammatory skin disease, IL-1β and IL-18 are increased, and excessive NLRP3 and caspase-1 expression levels are associated with its development." (PMID 39684233, 2024). "Analysis of differentially expressed genes in psoriatic lesions shows that NLRP3 holds significant diagnostic value for psoriasis." (PMID 39595526, 2024). "NLRP3 inflammasomes are associated with inflammatory skin diseases, including vitiligo, atopic dermatitis, and psoriasis." (PMID 39519119, 2024). "There was a highly significant difference in NLRP3 genotypes and alleles distribution between psoriasis patients and controls (P = 0.002,0.004)." (PMID 38965465, 2024). "In psoriasis, pathogenic T cells activate the NLRP3 inflammasome in keratinocytes, leading to the cleavage of pro-IL-1β by caspase-1 and the production of active IL-1β, which exacerbates skin inflammation." (PMID 38892253, 2024). "More research for evaluation of role of the NLRP3 gene polymorphism in the genetic risks and treatment outcomes associated with psoriasis is still required." (PMID 38965465, 2024). "There are many genetic studies supporting the role of NLRP3 in psoriasis susceptibility in patients." (PMID 39689159, 2024). "In psoriasis, IL-1β is mediated by an apoptosis-associated speck-like protein containing a caspase recruitment domain, such as NLRP3 and AIM2." (PMID 37465147, 2023). "For instance, genetic variations of the NLRP1 and NLRP3 inflammasomes have been associated with high levels of IL-1β in the lesions of patients suffering from psoriasis, vitiligo, and atopic dermatitis." (PMID 38068996, 2023). "The polymorphism of rs3806265 in NLRP3 is associated with several kinds of diseases, such as myasthenia gravis (MG), psoriasis, recurrent aphthous stomatitis (RAS) and relapsing–remitting multiple sclerosis (RRMS)." (PMID 35407478, 2022). "NLRP3 is an inflammasome implicated in a variety of inflammatory and autoimmune skin diseases including psoriasis and atopic dermatitis." (PMID 36618400, 2022). "The role of NLRP3 inflammasome in psoriasis pathogenic mechanism is complicated, and the researches are comparatively limited, which deserves further studies." (PMID 34707607, 2021). "The single nucleotide polymorphisms (SNPs) studies show that the genetic mutations in NLRP3 are associated with psoriasis susceptibility in Chinese Han population." (PMID 34707607, 2021). "They demonstrated—in a Swedish population—that certain polymorphisms in CARD8 (rs2043211) an NLRP3 (rs10733113) are strongly connected to the increase of psoriasis development risk and in patients with more widespread psoriasis." (PMID 34072753, 2021). "Sharon and Jiquan demonstrated a significant correlation of NLRP1 and NLRP3 gene polymorphism with psoriasis." (PMID 34790822, 2021). "The inflammasome sensor proteins NLRP-1 and NLRP-3 are expressed in psoriatic lesions and specific polymorphisms have been associated with psoriasis pathogenesis and susceptibility." (PMID 32903782, 2020). "Our results suggest that LPA5 is a novel pathogenic factor in psoriasis, along with its regulatory mechanisms in macrophage NLRP3 inflammasome activation." (PMID 32707926, 2020).
psoriasis (continued). "Polymorphisms in inflammasome and NFκB pathway associated genes, such as CARD14, NLRP1, and NLRP3, increase the individual's risk to develop psoriasis." (PMID 31333659, 2019). "Therefore, NLRP3 (rs10754558) gene polymorphism is an important prognostic biomarker in psoriasis patients." (PMID 38965465, 2024). "Differences involving the NLRP3 inflammasome have also been associated with psoriasis." (PMID 39337637, 2024). "The NLRP3 inflammasome has been associated with several diseases, such as psoriasis." (PMID 38965465, 2024). "NLRP3 polymorphisms have also been associated with psoriasis susceptibility." (PMID 39337637, 2024). "This research found a strong association between the GC genotype of NLRP3 and severe psoriasis." (PMID 38965465, 2024). "Furthermore, NLRP3 inflammasomes have been associated with various inflammatory and autoimmune skin disorders, including dermatitis, psoriasis, and acne." (PMID 37175425, 2023). "Next, we further explored whether the regulation of THL on IMQ‐induced psoriasis‐like symptoms in mice was associated with NLRP3 inflammasome activation." (PMID 37506136, 2023). "NLRP3 inflammasomes have been implicated in a wide range of pathologies and associated with symptomatologies, and are hyperactivated in individuals with autoimmune diseases, including psoriasis and corresponding fatigue." (PMID 35663672, 2022). "As such, modulating NLRP3 and associated pathways in psoriasis patients may have significant potential in the management of fatigue and improvement of life in patients with this condition." (PMID 35663672, 2022). "Alternatively, AP-1 might play a two-sided function in psoriasis; when the activation of NLRP3 is superior to the inhibition, the pathogenic NLRP3 inflammasome is produced." (PMID 35277199, 2022). "We firstly found that the IMQ-induced psoriasis-related female mice showed depressive- and anxiety-like behaviors, which were associated with microglial activation, the up-regulation of NLRP3, Caspase-1, IL-18, and IL-1β, and the down-regulation of CRMP2 and α-tubulin." (PMID 36138986, 2022). "Moreover, we have previously discovered the relationship between the genetic polymorphism of NLRP3 (rs3806265 and rs10754557) and psoriasis." (PMID 32104685, 2020). "Taken together, our in vitro results demonstrate that LPA/LPA5 signaling axis is associated with NLRP3 inflammasome activation in macrophages, strongly indicating that NLRP3 inflammasome activation is an underlying mechanism of psoriasis governed by LPA5 signaling." (PMID 32707926, 2020). "Moreover, the AIM2 inflammasome in keratinocytes also supports the development of psoriasis in humans, and even NLRP3 variants seem to play a role in psoriasis susceptibility." (PMID 32053878, 2020). "Moreover, research presented that miR-155 may induce psoriasis associated inflammatory responses via NLRP3 inflammasome activation." (PMID 34072753, 2021). "Therefore, activation of LPA5 signaling might contribute to skin injury in psoriasis, in which NLRP3 inflammasome activation could be an underlying mechanism." (PMID 32707926, 2020). "Additionally, NLRP3 polymorphisms have been associated with susceptibility to a number of different diseases, such as coal workers' pneumoconiosis, Crohn’s disease, sporadic malignant melanoma, psoriasis and many others." (PMID 26444566, 2015). "In psoriasis, studies suggest that macrophages can participate in disease progression through pyroptosis-related NLRP3 inflammasome activation." (PMID 40722833, 2025). "Pharmacodynamics results showed that 33.7% of NLRP3 locus had been disrupted, and psoriasis symptoms had obviously improved equally to calcipotriol ointment." (PMID 40299379, 2025). "Silencing NLRP3 gene can inhibit the proliferation of psoriasis-like HaCaT cells, arrest cell cycle, inhibit the expressions of cell proliferation-related proteins and reduce levels of pro-inflammatory factors." (PMID 41383588, 2025).